MCL1 (MCL1 apoptosis regulator, BCL2 family member)
Diseases named in the same sentence as MCL1 in open-access papers (continued):
Sharing a sentence is not in itself a finding about the gene and the disease.
colorectal cancer (74 papers, 2006 to 2025). A primary or metastatic malignant neoplasm that affects the colon or rectum. "Decreased degradation of MCL-1 is involved in the E3 ubiquitin ligase FBW7 mutation-induced resistance to regorafenib in colorectal cancer patients." (PMID 33883020, 2021). "MCL-1 expression is significantly increased in colorectal cancer and is associated with tumor stage, lymph node metastasis, and poor prognosis." (PMID 33883020, 2021). "The BRAF-mediated MEK/ERK-mediated MCL-1 upregulation is the production mechanism of colorectal cancer cell resistance that causes BRAF mutations." (PMID 34976824, 2021). "FBW7 mutation/deletion mediates resistance in colorectal cancer to targeted therapies by blocking Mcl-1 degradation." (PMID 29652830, 2018). "Previous studies showed a close association between Mcl-1 dysfunction and colorectal cancer; Mcl-1 ubiquitin degradation was considered as a key target of reversing the resistance of colorectal cancer." (PMID 28881661, 2017). "By targeting MCL-1 via mTOR inhibition, colorectal cancers with Kras or BRAF mutations are sensitized to BCL-2/BCL-XL inhibition." (PMID 26134786, 2015). "Additionally, the combination of the Mcl-1 inhibitor S63845 with ABT-263 can eliminate chemoresistance caused by abundant PCDH7 in colorectal cancer cells." (PMID 37063257, 2023). "Similarly, the overexpression of Mcl-1 is also an indicator of poor outcomes in colorectal cancer, as loss of Mcl-1 was found to be associated with increased expression of caspase- 3, 9 and also PUMA which is a proapoptotic protein." (PMID 36076273, 2022). "However, consistent with our CRISPR Activatory Screen, protein expression of antiapoptotic MCL-1 was significantly associated with resistance to MEDI3039 in the colorectal cancer panel (Spearman r = −0.73, P = 0.008)." (PMID 35086954, 2022). "Moreover, previous studies indicate that overexpression of Mcl-1 in human cervical and colorectal cancer tissues is associated with a poorer prognosis." (PMID 22266706, 2012). "In addition to BCL2, potent and highly selective small molecule inhibitors of its relatives, BCLxL and MCL1, are now available, prompting us to investigate the susceptibility of colorectal cancers to the inhibition of one or more of these pro-survival proteins." (PMID 32913182, 2020). "NVP-AUY922, a heat shock protein 90 (HSP90) inhibitor, enhances TRAIL induced apoptosis in colorectal cancer cells by inhibiting the JAK2-STAT3 Mcl-1 signaling pathway, and can also enhance the cytotoxic effects of various chemotherapy drugs in CRC." (PMID 40357363, 2025). "First, to our knowledge, this is the first study to demonstrate that MCL-1, an anti-apoptotic gene crucial for chemoresistance in colorectal cancer, undergoes dose-dependent downregulation in butyrate-treated CRC cells." (PMID 39859117, 2025). "Those authors described how MCL-1 inhibition sensitized treatment-resistant colorectal cancer cells to regorafenib." (PMID 39497108, 2024). "Apigenin increased the expression of Bim and decreased the expression of Mcl-1 in the colorectal cancer cell lines HCT116, which combined with the Bcl-2 inhibitor ABT-263 to cause mitochondria-dependent cell death." (PMID 38509538, 2024). "To further confirm that PCDH7 affected colorectal cancer chemoresistance mainly through Mcl-1 expression, we applied an Mcl-1 inhibitor, S63845, in HCT116 cells coupled with PCDH7 overexpression." (PMID 37063257, 2023). "In the present study, we found that PCDH7 conferred higher cell proliferation potential and stronger chemoresistance in colorectal cancer cells both in vitro and in vivo by promoting MCL-1 expression." (PMID 37063257, 2023). "In the present study, we found that the depletion of Skp2 (S-phase kinase-associated protein 2) enhances irradiation-induced apoptosis, accompanied by the decrease of the Mcl-1 protein level in human colorectal cancer cells." (PMID 35301297, 2022).
colorectal cancer (continued). "Trametinib also can enhance Mcl1 degradation-mediated apoptosis in combination with TRAIL in colorectal cancer cells." (PMID 34795217, 2021). "In mouse models of colorectal cancer with BRAF V600E mutations, cobimetinib combined with MCL-1 antagonists showed good drug-resistant antagonism." (PMID 34976824, 2021). "PMAIP1 is involved in the intrinsic apoptosis pathway, selectively binds to MCL1, and prevents MCL1 to inhibiting apoptosis in colorectal cancer." (PMID 33506057, 2021). "In concordance with these results, miR-193a belonging to the same miRNA family as miR-193b has also been shown to directly target MCL1 mRNA in the context of dexamethasone-resistant MM cell lines and colorectal cancer." (PMID 33806619, 2021). "MCL-1 inhibitors synergize with standard therapies to exert antitumor activity in colorectal cancer." (PMID 33883020, 2021). "MCL-1 inhibitor A-1210477 in combination with cobimetinib reverses colorectal cancer drug resistance and enhances cobimetinib-induced apoptosis." (PMID 33883020, 2021). "We previously showed that resistance to regorafenib, a multi-kinase inhibitor for treating colorectal cancer (CRC) patients, can be caused by mutations in the tumor suppressor FBW7, which block degradation of the pro-survival Bcl-2 family protein Mcl-1." (PMID 32724460, 2020). "While targeting BCLxL, but not BCL2 or MCL1, on its own had some impact, most (15/17) of the immortalized colorectal cancer cell lines studied were efficiently killed by the combined targeting of BCLxL and MCL1." (PMID 32913182, 2020). "Our results lend strong support to the notion that BCLxL and MCL1 are highly promising targets for further evaluation in efforts to improve the treatment of colorectal cancers." (PMID 32913182, 2020). "Mcl1 inhibitors increase the sensitivity of FBW7-mutant colorectal cancer cells to various targeting agents." (PMID 29652830, 2018). "Intriguingly, depletion of antiapoptotic BCL-2 proteins such as BCL-2, BCL-xL, and MCL-1 in colorectal cancer cells fail to suppress cell proliferation." (PMID 28035994, 2016). "We therefore propose that Mcl-1 targeting should be considered in the future to reduce senescence escape and to improve the treatment of irinotecan-refractory colorectal cancers." (PMID 25565667, 2015). "We surveyed the percentage of copy number alternations of BCL2, BCL2L1 and MCL1 among a majority of these tumor samples and found that colorectal cancer has the highest percentage of BCL2L1 gain/amplification among all cancer types." (PMID 26134786, 2015). "Strikingly, we demonstrate a profound impairment of both, migration and invasion, of colorectal cancer cells after Mcl-1, Bcl-2 or Bcl-xL knockdown." (PMID 24098503, 2013). "Data herein delineate the molecular process by which CXCL12 re-expression regulates Bim and Mcl-1 to initiate anoikis in colorectal cancers." (PMID 20877573, 2010). "Conversely, upregulation of Mcl-1 in colorectal carcinomas results in diminished efficacy of chemotherapy treatments such as 5-fluorouracil and has been shown to mediate anoikis resistance in other cancer types." (PMID 20877573, 2010). "Taken together, although PCDH7 inhibited the migration and invasion of CRC cells, it could facilitate the development of drug resistance in colorectal cancer cells by positively modulating Mcl-1 expression." (PMID 37063257, 2023). "Our previous study also showed that Skp2 stabilizes Mcl-1 and thus confers radioresistance to colorectal cancer, suggesting that targeting Mcl-1 could be an extremely promising strategy for cancer treatment." (PMID 37259388, 2023). "Importantly, roburic acid inhibited the TNF-induced phosphorylation of IKKα/β, IκBα, and p65, degradation of IκBα, nuclear translocation of p65, and NF-κB-target gene expression, including that of XIAP, Mcl-1, and Survivin, in colorectal cancer cells." (PMID 35222445, 2022).
colorectal cancer (continued). "Interestingly, BCL-xL levels, associated with poor prognosis in liver and colorectal cancer, and the BCL-xL/MCL-1 ratio were detected as being increased in HCC patients." (PMID 32024199, 2020). "Through which signal pathway that MCL1 participated in tumor metastasis and whether other promising targets of miR-125b existed in colorectal cancer need a further investigation." (PMID 28881590, 2017). "Likewise, the levels of Noxa-antagonist Mcl1 were not repressed by the treatment with CPT and/or SM83, and further experiments confirmed an increased stability of Mcl1 in colorectal cancer compared to HME cells." (PMID 26028667, 2015). "Furthermore, in a colorectal cancer cell, the anti-apoptotic MCL1 has been reported to be regulated (in vitro) by a number of miRNAs, including miR-876-3p which we predicted to be shared by MEG3 and MCL1." (PMID 24926662, 2014). "Moreover, Mcl-1 expression predicts response to anti-cancer treatment, e.g. in chronic lymphocytic leukemia or patients with metastasized colorectal cancer." (PMID 17014711, 2006). "Similarly, c-Myc and Mcl-1 responses to glutamine and QARS were observed in LOVO and SW1116 colorectal cancer cells harboring Gln-K604-intact FBW7 point mutations, suggesting that the loss of Gln-K604 contributes to the upregulation of c-Myc and Mcl-1 expression." (PMID 40338031, 2025). "To evaluate whether sensitivity to AZ’1569 correlated with expression levels of proapoptotic and antiapoptotic BCL-2 family members or DR_MOMP stress dose, we initially determined the basal absolute BCL-2 proteins profiles (BAK, BAX, BCL-2, Bcl-xL, MCL1) in our KRASG12CMT colorectal cancer cells." (PMID 36279564, 2023). "For instance, fisetin controls miR-3664-3p expression in HCT116 cells, thereby decreasing drug resistance of colorectal cancer cells by targeting ABCG2, CYP3A4, MCL1, and MLH1." (PMID 41470858, 2025). "Unlike the defective apoptotic machinery reported in some AML and colorectal cancer subsets, all tested GC lines were effectively killed by the triple combination of BCL2, BCLXL, and MCL1 inhibitors." (PMID 40075071, 2025). "Among the genes examined, Ki-67, MCL-1, and PCNA have rarely been the primary focus in studies investigating the effect of sodium butyrate on colorectal cancer cells." (PMID 39859117, 2025). "In line with our findings, co-inhibition of MCL-1 and BCL-xL showed stronger cytotoxicity in many sarcomas and other cell lines, including those derived from colorectal cancer (CRC) and cervical cancer, compared to co-inhibition of BCL-2/BCL-xL or MCL-1/BCL-2." (PMID 39497108, 2024). "In colorectal cancer cells, BETi treatment led to repression of MYC-driven expression of miR1271-5p, which in turn led to increased NOXA levels and inhibition of MCL-1, thereby enabling synergy with ABT-263." (PMID 33799592, 2021). "In BRAFV600E-mutant colorectal cancer, mutant BRAF upregulates MCL-1 to confer apoptosis resistance." (PMID 33883020, 2021). "The MCL-1 inhibitor S63845, AZD5991, AMG-176 restore sensitivity to regorafenib in FBW7 mutant colorectal cancer cells by restoring the apoptotic response." (PMID 33883020, 2021). "In previous studies, magnolol induced downregulation of Mcl-1 and c-FLIP expression, and inhibited tumor progression of colorectal cancer." (PMID 33050112, 2020). "The combination of small molecules including imatinib targeted MCL1 and celecoxib targeted PDPK1 was reported to treat the HT30 colorectal cancer." (PMID 32523951, 2020). "Due to the inhibitory effect of MCL1 on BAK, the apoptosis of HCT116 colorectal cancer cells in response to either ABT-73729 or the BCL-XL inhibitor A1331852 relies on BAX." (PMID 30478310, 2018). "Both, Bcl-XL and Mcl-1 have been identified as interaction partners of TCTP, and they have been shown to contribute to enhanced resistance of colorectal cancer cells against 5-FU and oxaliplatin." (PMID 28143584, 2017).
colorectal cancer (continued). "AZD8055, an mTORC1/2 inhibitor, reduces MCL-1 expression in KRAS- and BRAF-mutant colorectal cancer cells." (PMID 28659182, 2017). "In order to investigate the expression of the antiapoptotic Bcl-2 proteins Mcl-1, Bcl-2 and Bcl-xL in human CRC cell lines, we measured protein levels in four colorectal cancer cell lines." (PMID 24098503, 2013). "We used migration and invasion assays as well as three dimensional cell cultures to analyze colorectal cancer cell lines (HT29 and SW480) after siRNA mediated knockdown or overexpression of Mcl-1, Bcl-2 or Bcl-xL." (PMID 24098503, 2013). "The SAM programme typed the following genes to be statistically significant in the compared groups as genes differentiating stage I and II of clinical progression of colorectal cancer: AKT1, STAT3, MCL1, and STAT5B." (PMID 22363883, 2011). "Our study also reveals the ratio of MCL1:BCL-XL is similar between thyroid and colorectal cancer, suggesting that colorectal cancer may also benefit from this triple-combination therapy." (PMID 36672327, 2023). "To identify the best BH3 mimetic strategy, we analyzed mRNA ratios of MCL1 and BCL-XL, based on a previous study that showed a low ratio of MCL1:BCL-XL, in colorectal cancer (CRC) correlated with synthetic lethality between ERK pathway inhibitors and pan BCL-2 inhibitors." (PMID 36672327, 2023). "Because the Mcl-1 and Wnt/β-catenin signaling pathways were molecularly identified as regulatory targets of PCDH7, we discovered a combination of the Mcl-1 inhibitor S63845 and ABT-263 as a novel chemotherapy treatment option for PCDH7-high colorectal cancer." (PMID 37063257, 2023). "In colorectal cancer, overexpression of miR-125b-5p using mimics in CRC cell lines significantly inhibited the proliferation, triggered G2/M cell cycle arrest, induced apoptosis, and promoted cell migration and invasion via direct targeting MCL1." (PMID 28968424, 2017). "However, a conflict result has been reported recently that DCA decreases the level of Mcl-1 in AML cells and colorectal cancer cells." (PMID 27449090, 2016). "The aim of this study was to dissect a potential role of the antiapoptotic Bcl-2 proteins Mcl-1, Bcl-2 and Bcl-xL on migration and invasion of colorectal cancer cells independent of their cell death control function." (PMID 24098503, 2013). "The data presented indicate a pivotal role of Mcl-1, Bcl-2 and Bcl-xL for migration and invasion of colorectal cancer cells independent of their known antiapoptotic effects." (PMID 24098503, 2013). "Based on this study we conclude that Mcl-1, Bcl-2 and Bcl-xL contribute to migration and invasion of colorectal cancer cells independent of their antiapoptotic effects." (PMID 24098503, 2013). "Both FLIP and MCL-1 are highly turned over at the protein level which may explain why their protein levels but not their mRNA levels correlated more strongly with sensitivity to MEDI3039 in the colorectal cancer panels." (PMID 35086954, 2022). "In addition, roburic acid induced the apoptosis of colorectal cancer cells by promoting the cleavage of PARP, Caspase3, Caspase7, and Caspase9, as well as downregulating the levels of the antiapoptotic proteins Bcl-2, Bcl-xL, XIAP, Mcl-1, and Survivin." (PMID 35222445, 2022). "Whether BCL2, or its close relatives such as BCLxL or MCL1, is critical for maintaining the survival of solid cancers, including colorectal cancers (CRCs), is not fully defined." (PMID 32913182, 2020). "This is accompanied by suppression of MCL1 expression in mutant, but not WT, colorectal cancers." (PMID 26636651, 2015).
colorectal cancer (continued). "As anticipated, the protein expression of Mcl-1 was upregulated following PCDH7 overexpression in HCT116 cells and downregulated after PCDH7 knockdown in RKO cells, which may partially explain the anti-apoptotic effect exerted by PCDH7 on colorectal cancer cells." (PMID 37063257, 2023). "Moreover, CDK9 inhibition by Dinaciclib resulted in markedly decreased colorectal cancer cell viability and profoundly enhanced TRAIL-mediated apoptosis of resistant colorectal cancer cells via suppression of short-living anti-apoptotic proteins Mcl-1 and c-FLIP." (PMID 36979907, 2023). "In the study of a large cohort of colorectal cancers, BCL-XL, but not BCL2 or MCL-1, emerged as a highly active protein, and its transcript level was the highest among the anti-apoptotic BCL2 genes." (PMID 34202143, 2021). "Moreover, a significant correlation between the CASP8/MCL-1 protein ratio and sensitivity to MEDI3039 was observed in the colorectal cancer panel, although this failed to reach significance at the mRNA level." (PMID 35086954, 2022).